IL10 (interleukin 10)
Diseases named in the same sentence as IL10 in open-access papers (continued):
Sharing a sentence is not in itself a finding about the gene and the disease.
Arthritis (continued). "A total of 6 mg/kg/d for 22 days improved foot-plantar swelling and arthritis scores in RA rats and regulated the balance of pro-inflammatory factors, such as IL-1β, IL-6, and IL-17A, and anti-inflammatory factors, such as IL-4 and IL-10." (PMID 40864815, 2025). "In addition, a high-fiber diet rich in resistant starch (RS) increases the abundance of Bacteroides and circulating propionate, thereby promoting the increase of Treg cells and the production of IL-10 and improving arthritis in CIA mice." (PMID 40692793, 2025). "The faster resolution of arthritis was attributed to altered activation of Fas-deficient macrophages by IL -1β and the endogenous TLR2 ligand gp96 and overexpression of anti-inflammatory IL-10." (PMID 40443734, 2025). "Those authors showed that MSCs treatment induced a more regulatory phenotype with the production of IL-4 and IL-10, but also of IFN-γ, and a systemic decrease of pathogenic antibodies, thus demonstrating the potential value of MSCs treatment in resistant arthritis." (PMID 40493163, 2025). "Furthermore, exosomes (exos) derived from human gingival MSCs (GMSCs) exhibited comparable or enhanced efficacy compared with GMSCs in suppressing IL‐17A and enhancing IL‐10 production, thereby reducing the incidence of arthritis and bone erosion." (PMID 38712483, 2024). "Following the observation of increased serum levels of IL10, as well as increased frequency of IL10+ cells in the DUSP6 KO mice, we hypothesized that IL10 was mediating the arthritis-protective effect observed in DUSP6 KO mice." (PMID 38974475, 2024). "To conclude, DCs transfected with DNA constructs encoding epitopes of type II collagen, IL-10, and CCR9 promote antigen-specific tolerance, control inflammation, and reduce the severity of experimental arthritis through the induction of T regulatory cells, IL-10, and TGF- β." (PMID 39161770, 2024). "Arthritis protection in the high Mg diet was also associated with decreased expression of the pro-inflammatory cytokines TNFα, IL1β, and IL6 and increased numbers of IL10-producing Tr1 and Foxp3+ Treg cells." (PMID 39683640, 2024). "In addition, butyrate was already shown to reduce arthritis severity via the stimulation of AhR in IL-10-producing regulatory B cells." (PMID 38046818, 2023). "In addition to type I IFN, interleukin 10 (IL-10), an anti-inflammatory cytokine, has a crucial role in the regulation of arthritis severity." (PMID 37113133, 2023). "While IL-10 which is an anti-inflammatory cytokine is upregulated with Toxoplasma infection, as discovered in many studies, to suppress host immunity for infection survival, the same effect appeared on arthritis model." (PMID 37389660, 2023). "They demonstrated that the systemic administration of DC-derived exosomes treated with IL-10 could prevent the development of arthritis induced with murine collagen and lessen the severity of pre-existing arthritis." (PMID 37111636, 2023). "In addition, in mouse models of arthritis, IL-10 was identified to inhibit the occurrence and progression of arthritis." (PMID 36789002, 2023). "To investigate whether a change in β2-ADR expression is accompanied by an increase in IL-10, we additionally analyzed the amount of IL-10-expressing B cells and the IL-10 density during course of arthritis by flow cytometry." (PMID 36009497, 2022). "In addition, the CFA + MTX-GNPs group showed a noticeable elevation of serum IL10 by 190.18% compared to the CFA-arthritis group." (PMID 36678557, 2022). "The results suggested that 5-azacitidine could improve arthritis pathogenesis by upregulating expression of the antiinflammatory cytokine IL-10 and inhibiting IgG1 production." (PMID 35472067, 2022). "Correlation analysis revealed that both Lachnospiraceae_NK4A136_group and uncultured_bacterium_f_Ruminococcaceae were positively correlated to the content of pro-inflammatory cytokines, paw swelling and arthritis scores while negatively correlated to the content of IL-10." (PMID 35864275, 2022).
Arthritis (continued). "IL-10 has been detected in synovial membrane and fluids of RA individuals—it is possible that cytokine is powerful enough to control acute inflammation, but becomes inadequate in case of constant stimulation that accompanies arthritis." (PMID 35179632, 2022). "In conclusion, use of IL-10-edited human AMM/I may be a novel therapeutic strategy for the treatment of arthritis." (PMID 35887258, 2022). "In addition, IL‐10 emerges as another robust indicator of inflammatory status in arthritis muscle, while arthritis‐ascribed differences in other pro‐inflammatory cytokines disappeared when expressing data on a per fiber basis." (PMID 34806343, 2021). "Similarly, oral administration of triterpenoid saponin, madecassoside provided anti-arthritis effects through enhanced secretion of IL-10 from the small intestine of collagen induced arthritis rats and the accumulation of Foxp3+ cells in the lamina propria." (PMID 34479568, 2021). "Interestingly, microbiota-derived 5 Hydroxyindole-3-acetic acid (5-HIAA) suppressed murine arthritis by expanding AhR+IL-10+CD19+CD21hiCD24hi Bregs, suggesting the importance of microbes in the maintenance of Bregs." (PMID 33936028, 2021). "Next, we examine whether Treg and IL-10 were involved in the AAV8.CII-mediated reduction of the arthritis phenotype." (PMID 34521922, 2021). "In fact, work from our group has demonstrated that neutrophil-derived EVs, which display anti-inflammatory activity, can be loaded with therapeutic cargo including anti-TNF-α as well as IL-10 and targeted to arthritic joints using cartilage specific antibodies to improve experimental arthritis." (PMID 32993051, 2020). "It was subsequently suggested that madecassoside may exhibits anti-arthritis potency through affecting the secretion of IL-10 from Foxp3+ cells in lamina propria of intestine, thus regulates the immune function of rats with collagen-induced arthritis." (PMID 33013406, 2020). "There is some evidence that changes in IL-10 may contribute to this protection and the relationship between kynurenines and IL-10 in arthritis and other inflammatory conditions should be explored." (PMID 32194572, 2020). "Increased IL-10 production was correlated with decreased IFNγ cytokine production suggesting that these HSP70 may have potential to reduce disease severity in arthritis patients." (PMID 33348708, 2020). "In collagen-induced arthritis model, MZ B cells produce most of IL-10 in response to TLR stimulation or apoptotic cells, and the adoptive transfer of MZ B cells could protect mice from infection." (PMID 32973780, 2020). "Since IL‐10 regulates arthritis development, we speculated that IL‐10 is involved in the osteogenic capacity of MC3T3‐E1 cells." (PMID 31755174, 2020). "Having confirmed the contribution of AhR in the programming of the IL-10+CD19+CD21hiCD24hiBreg transcriptional profile, we explored the impact of AhR deficiency specifically in B cells on the immune response associated with arthritis." (PMID 31722204, 2019). "The recognised IL-10 distinctive capacities to downregulate the production of pro-inflammatory cytokines meant that it has been regarded as a potential therapeutic agent for the treatment of arthritis." (PMID 30804924, 2019). "In the context of arthritis, splenic Bregs have been shown to produce mainly IL-10." (PMID 31722204, 2019). "Reduced circulating and lymph nodes CD4+IL-10+ T cells have been reported in subjects at risk for RA, with a subsequent increase in peripheral CD4+IL-17A+ T cells in close relationship with the onset of the arthritis." (PMID 31295951, 2019). "Moreover, IL-10 secretion by MSCs is critical for their immunomodulatory functions in immune disease models, including those for arthritis." (PMID 30092847, 2018). "Conversely, IL-22 administration in CIA mice inhibits arthritis through enhanced IL-10 expression." (PMID 30619268, 2018).
Arthritis (continued). "Here the authors show that, alternatively, Bregs may also present lipid antigens on surface CD1d to induce IFN-γ production from invariant natural killer cells to ameliorate experimental arthritis via IL-10-independent pathways." (PMID 29449556, 2018). "IL-10-producing Tregs ameliorate collagen-induced arthritis in mice." (PMID 28511719, 2017). "Moreover, IL-10 is a good candidate transgene to suppress arthritis using disease-regulated promoters." (PMID 28316377, 2017). "We also investigated whether IL-10 is responsible for limiting IL-33/ST2 elicited joint inflammation in CIA." (PMID 28415811, 2017). "Transferring B10 to IL-10 knockout mice inhibited Th1 response in arthritis." (PMID 28428789, 2017). "In addition, studies conducted on the animal model of arthritis reveals the beneficial effect of IL-10 on the reduction of severity of arthritis." (PMID 28594861, 2017). "It was reported that B cell-deficient or lacking IL-10-producing B cells mice developed exacerbated arthritis and did not recover from experimental autoimmune encephalitis." (PMID 28477096, 2017). "Another limitation in our study was that IL‐10 production may be altered in many children with arthritis because of the treatment they receive, which includes both glucocorticoids and MTX; these are both known to affect IL‐10 production." (PMID 28257625, 2017). "Furthermore, our analysis identified predicted target genes of DE miRNAs in PMECs at 3 hpc with E. coli that are enriched in top canonical pathways such as IL-10 signaling, PPAR signaling, NF-ĸB signaling, TNFR2 signaling, or arthritis-associated roles." (PMID 28836962, 2017). "Transfer of immature T2 cells from mice with arthritis at the remission stage could help recover the balance between Treg and Th1/Th17 responses in IL-10−/− hosts." (PMID 28751919, 2017). "However, the extent of disease activity seen in WT and Il10-/- mice remains comparable during the first two weeks following arthritis induction." (PMID 37220589, 2016). "In addition, chimeric mice specifically lacking IL-10 producing B cells were reported to develop an exacerbated collagen-induced arthritis and to have a reduction in IL-10 secreting Tr1 cells compared to wild type mice." (PMID 27472281, 2016). "Thus, in this study, it has been possible for the first time to determine the role of IL-10 in behavioral control during experimental arthritis." (PMID 37220589, 2016). "We hypothesized that the inability of IL-10 to suppress miR-155 during Lyme arthritis development could be contributing to increased arthritis severity." (PMID 26252010, 2015). "Here we demonstrated that exogenous treatment with FBP markedly attenuates arthritis, reducing joint swelling, neutrophil infiltration, articular hyperalgesia and pro-inflammatory cytokine production, while boosting IL-10 production in two experimental models of arthritis." (PMID 26478088, 2015). "IL-10 has been shown to be an important modulator of disease; Il10-/- mice develop more severe LA than wild-type B6 mice, and arthritis in these mice is accompanied by high cytokine levels, low bacterial numbers, and a robust T cell response and IFNγ signature." (PMID 26252010, 2015). "Injection of lentiviral vectors expressing the IL-10 gene under inflammation-dependent promoters such as Saa3 and Mmp13 intra-articularly into knee joints of mice resulted in reduced synovitis and cartilage proteoglycan depletion in experimental arthritis." (PMID 25561237, 2014). "We therefore examined the synovial regulation of inflammasome components by IL-10 during arthritis." (PMID 25175678, 2014). "In a recent study N. sativa had increased both the IL-10 and TNFα concentration in normal rats, but in another study thymoquinone (N. sativa’s major bioactive component) reduced TNFα and increased IL-10 in the rat’s arthritis model." (PMID 25380621, 2014).
Arthritis (continued). "In addition, in models of arthritis and colitis, IL-10-producing B cells have been shown to possess disease modulating capability 12,13." (PMID 24945741, 2014). "Furthermore, B6 IL10−/− mice, a model for Th1-mediated arthritis, have a very pronounced IFNγ signature beginning at 14 days post-infection that persists for several weeks." (PMID 24967703, 2014). "The described products may represent useful research tools for the study of the anti-arthritic properties of TNF blockade and of IL10-based immunocytokines in syngeneic immunocompetent models of arthritis." (PMID 24289726, 2013). "Posttreatment with IL-10 reduced the swelling in collagen type II-induced arthritis." (PMID 23634171, 2013). "These in vivo evidence suggested that the beneficial effect of CGS 21680 in experimental arthritis could be due, at least in part, to the increase of IL-10 which counterbalance the overexpression of inflammatory mediators." (PMID 23326596, 2013). "Since B cells stimulated with IL-5 and CD40L secrete IL-10 and are potent inducers of apoptosis in activated T cells, we have made several attempts to assess their immunosuppressive function in vivo by adoptive transfer in a collagen-induced arthritis model." (PMID 23940537, 2013). "Infection studies using B6 mice lacking a functional IL-10 gene (IL-10-/-) showed these animals developed increased ankle swelling and arthritis severity compared to wild-type controls, even though the IL-10-/- mice maintained ~10-fold less bacteria in affected tissues." (PMID 24367705, 2013). "Others have shown that mice lacking IL10-producing B cells develop an exacerbated antigen-induced arthritis, which is also associated with reduced numbers of Tregs and increased Th1 and Th17 cells." (PMID 23755918, 2013). "Furthermore, administration of an agonistic antibody against CD40 improves arthritis by the provision of IL-10 and IL-10 mediated TH1 inhibition." (PMID 22969768, 2012). "In addition, joint levels of TGFβ1, IL-10, IFNγ, IL-4 and IL-17 mRNAs were augmented in WT mice with arthritis." (PMID 22438945, 2012). "Sonderegger and colleagues further showed the infiltration of inflammatory cytokines/chemokines and IFN-γ-producing cells in joint tissues of infected C57 IL-10 -/-, contributed to their arthritis development, substantiating IFN-γ synergy with spirochetes to promote inflammation." (PMID 23024745, 2012). "Finally, we previously showed that IL-10 ameliorates S. aureus arthritis in mice, and others demonstrated that estradiol ameliorates adjuvant-arthritis in rodents in conjunction with an increased IL-10 response." (PMID 22507741, 2012). "The reduction in arthritis in LNT-IL-10 mice suggested that IL-10 is produced." (PMID 23166758, 2012). "In contrast, induction of arthritis decreased IL-10 in all three genotypes." (PMID 23285041, 2012). "Whether the B cells in the LNT-IL-10 mice are IL-10- producing regulatory B cells is currently unknown, although it is possible as such cells have been found to reduce the severity of arthritis." (PMID 23166758, 2012). "Collectively, the in vivo and in vitro experiments confirm that the suppression of arthritis by A12-specific T cells involves active secretion of suppressive cytokines (specifically IL-4 and IL-10), resulting in a downregulation in the inflammatory cytokines IL-17 and IFN-γ." (PMID 22569209, 2012). "In comparison with preclinical arthritis rats, Bhsp65-tolerized rats showed downregulation of Th1 and Th17 (proinflammatory response) and of other mediators of inflammation and angiogenesis, but upregulation of IL-10 (anti-inflammatory and immunoregulatory)." (PMID 21914168, 2011). "In IL-10 deficient mice HSP70 immunization did not suppress arthritis illustrating the IL-10 dependency of HSP70 induced immuno-regulation." (PMID 19142233, 2009).
Arthritis (continued). "In the present study the protective potential of mycobacterial HSP70 immunization on inflammatory disease and its dependency on IL-10 were assessed in the proteoglycan-induced arthritis model (PGIA), a progressive T cell dependent, antibody-mediated murine model for RA." (PMID 19142233, 2009). "In this study transfer of cells expressing IL-10 after retroviral IL-10 gene transduction could suppress arthritis." (PMID 19142233, 2009). "The important role of IL-10 in arthritis has been studied previously in the PGIA model." (PMID 19142233, 2009). "Mean day of onset and maximum arthritis score in WT and IL10−/− mice." (PMID 19142233, 2009). "Animal studies implicate IL-10 in the development and progression of arthritis and chronic colitis." (PMID 17239241, 2007). "MiR-155 expression is suppressed by IL-10, a potent anti-inflammatory cytokine; in a murine model of LD, IL-10 and miR-155 have opposite effects on the development of carditis, although both were required for the suppression of carditis and MiR-155 had little effect on arthritis." (PMID 40732111, 2025). "This study is representative of the roles of IL-17A and IL-10 polymorphisms, mainly in the oligoarthritis and polyarthritis types of JIA (which are the two major groups) in a Finnish population, as the numbers of ERA patients and other types of arthritis were low." (PMID 39125893, 2024). "Moreover, the suppression of arthritis development seemed to be IL-10 production dependent." (PMID 38691538, 2024). "In our experiment, LBP relieved the typical features of RA in rats, including the reduction of paw swell, arthritis scores and the contents of pro-inflammatory cytokines such as IL-1α, IL-1β, IL-12 and IL-17, and the recovery of the content of anti-inflammatory cytokine IL-10." (PMID 35864275, 2022). "Additionally, IL-10-transduced murine MSCs inhibit experimental arthritis." (PMID 35887258, 2022). "In a mouse collagen induced arthritis model, apoptotic cell therapy delayed the clinical onset and protected mice from severe joint inflammation and bone destruction through this mechanism where inhibition of IL-10 in vivo reversed the beneficial effects of apoptotic cells." (PMID 33717145, 2021). "Thus, our data indicated that G-exo promoted IL-10+ B cells generation but inhibited Tfh and plasma cells, which may contribute to the remission of arthritis." (PMID 33329572, 2020). "Similarly, AhR deficiency restricted to B cells impairs IL-10+CD19+CD21hiCD24hiBreg differentiation and function, resulting in an increase of IFNγ and IL-17-expressing CD4+ T cells, a decrease in Tregs, and the development of an exacerbated arthritis." (PMID 31722204, 2019). "In addition, stimulating PBMCs with the immunopromoting epitope in the presence of the immunoregulatory epitope reduced IL-17 and IFNγ production, and introducing the immunoregulatory peptide orally in a collagen induced arthritis model led to increased IL-10 and T regulatory cells." (PMID 30978945, 2019). "In murine models of arthritis, for instance, active immunization with bacterial or autologous Hsp70—which obviously generated Hsp70-specific immunoglobulins—prevented and arrested the disease symptoms and attenuated inflammation response via induction of IL-10 and Tregs." (PMID 31073900, 2019). "Furthermore, reversion of arthritis by IL-10 was not limited to AIA." (PMID 30804924, 2019). "Interestingly, in a murine model of delayed-type hypersensitivity and collagen-induced arthritis, EVs containing adenovirus expressing viral IL-10 or bone marrow-derived DCs treated with recombinant murine IL-10 suppressed the inflammatory and autoimmune responses when injected particularly." (PMID 30035185, 2018). "Since the suppression of TNF-α production and augmentation of IL-10 expression are thought to be a favorable approach for treating RA, we speculated that the administration of TJ-20 could be an ideal therapy for arthritis." (PMID 28555160, 2017).